NME7 (NME/NM23 family member 7)
Description:
Possesses an intrinsic kinase activity. Phosphorylates GSK3B at 'Ser-9', leading to the activation of Wnt/beta-catenin signaling. Additionally, exhibits a 3'-5'-DNA exonuclease activity that removes single nucleotides from the 3' terminus of single-stranded DNA substrates and digests overhanging mismatched 3' termini from double-stranded DNA substrates, possibly participating in DNA nucleolytic processing. In vitro, does not seem to have nucleoside diphosphate kinase activity. Functional component of the gamma-tubulin ring complex, implicated in the regulation of its microtubule-nucleating activity in centrosomes, in a kinase activity-dependent manner. May maintain primary cilium assembly and ciliary microtubule stability. Part of the dynein-decorated doublet microtubules (DMTs) in cilia axoneme, required for motile cilia beating.
Synonyms: NDK7; FLJ37194; NM23-H7; CFAP67; MN23H7; NDK 7
Tractability: Small molecule: a structure with a bound ligand is known. Antibody: its Gene Ontology location is reachable by antibodies, with medium confidence. PROTAC: ubiquitination databases record sites on it; its protein half-life has been measured.
Gene: Protein-coding gene on chromosome 1 (169,132,531 to 169,367,948, reverse strand). Ensembl gene ENSG00000143156.
Subcellular location: Cytoplasm, cytoskeleton, microtubule organizing center, centrosome; Nucleus; Cytoplasm; Cytoplasm, cytoskeleton, spindle; Cytoplasm, cytoskeleton, cilium axoneme; Cytoplasm, cytoskeleton, flagellum axoneme; Cell projection, cilium; Cytoplasm, cytoskeleton, cilium basal body
Subcellular location (Human Protein Atlas): Nucleoplasm; Cytosol
Pathways (Reactome):
Cell Cycle: Recruitment of NuMA to mitotic centrosomes; Recruitment of mitotic centrosome proteins and complexes
Gene Ontology:
Molecular function: 3'-5'-DNA exonuclease activity; nucleoside diphosphate kinase activity; protein binding; protein kinase activity; protein serine kinase activity; ATP binding; protein serine/threonine kinase activity
Biological process: cilium assembly; DNA catabolic process; regulation of microtubule nucleation; flagellated sperm motility; CTP biosynthetic process; GTP biosynthetic process; UTP biosynthetic process
Cellular component: axonemal microtubule; centrosome; ciliary basal body; cilium; cytoplasm; cytosol; gamma-tubulin ring complex; nucleoplasm; nucleus; axonemal A tubule inner sheath; sperm flagellum; axoneme; spindle
Genetic constraint (gnomAD): Loss-of-function variants: 13 observed, 17.27 expected, observed/expected ratio (o/e) 0.75, 90% interval 0.49 to 1.2. The upper end of that interval is the gene's LOEUF score, 1.2, which puts it in group 5 of 6, group 1 being the genes least tolerant of losing a copy. Missense variants: 226 observed, 251.11 expected, observed/expected ratio (o/e) 0.9, 90% interval 0.81 to 1. Synonymous variants: 84 observed, 87.93 expected, observed/expected ratio (o/e) 0.96, 90% interval 0.8 to 1.14.
Homologues: Orthologues: chimpanzee NME7 (99% identical), dog NME7 (94% identical), guinea pig NME7 (93% identical), pig NME7 (93% identical), macaque NME7 (91% identical), mouse Nme7 (88% identical), rat Nme7 (88% identical), tropical clawed frog nme7 (68% identical), zebrafish nme7 (66% identical), Drosophila melanogaster nmdyn-D7 (39% identical). Paralogues in human: NME8 (26% identical), NME5 (19% identical), NME6 (17% identical), NME4 (13% identical), NME1 (13% identical), NME3 (12% identical), NME2 (12% identical), NME9 (10% identical).
Diseases named in the same sentence as NME7 in open-access papers:
NME7 is named in the same sentence as 26 diseases in open-access papers, as found by Europe PMC text mining. Sharing a sentence is not in itself a finding about the gene and the disease. The quoted sentences say what the papers report.
Hydrocephalus (6 papers, 2019 to 2025). Hydrocephalus is an active distension of the ventricular system of the brain resulting from inadequate passage of CSF from its point of production within the cerebral ventricles to its point of absorption into the systemic circulation. "Nme7 knockout mice displayed situs inversus with left–right transposition of visceral organs and associated vasculature, in addition to hydrocephalus and excessive nasal exudates, which are signs of defective cilia." (PMID 39824631, 2025). "In the Nme7 knock-out mice model and the reported human Nme7 homozygous mutation carriers, hydrocephalus and situs inversus were the most apparent features." (PMID 33916973, 2021). "Consistently, depletion of NME7, a nucleoside diphosphate kinase fitted into the density maps of both mBMIP3 and mBMIP3L, in rats has recently been shown to cause ciliopathies, including severe hydrocephalus, reversed internal organ arrangement, and sterility." (PMID 40593728, 2025). "The phenotypes arising from NME7 deficiency range from situs inversus was reported in two siblings from a consanguineous family, through situs inversus, hydrocephalus and excessive nasal exsudates in mice to situs inversus, sterility and massive hydrocephalus leading to premature death in rats." (PMID 34356103, 2021). "Homozygous Nme7 gene deletion in rats was semilethal and displayed multiple symptoms of primary ciliary dyskinesia, including hydrocephalus, situs inversus totalis, postnatal growth retardation, and sterility in both sexes." (PMID 39824631, 2025). "The CRISPR/Cas-9-mediated knock-out of the Nme7 gene in SD rats led to severe hydrocephalus, situs inversus, sinopulmonary disease, infertility of both sexes, and a range of morphological and metabolic dysregulations." (PMID 33916973, 2021). "Nme7−/− mice developed situs inversus and hydrocephalus, which indicates a role of Nme7 in biogenesis or a function in motile cilia." (PMID 31877804, 2019). "Genes like cyclin O (CCNO), NME/NM23 family member 7 (NME7), and huntingtin (HTT) are also involved in centriole amplification, γ-tubulin ring complex activity, and centrosomal organization, and their disruption can cause failure in cilia development and hydrocephalus." (PMID 40722587, 2025). "Interestingly, disruption of Nme7 in mice led to situs inversus, only mild hydrocephalus, and no impairment of fertility, and situs inversus was reported in a family with a homozygous deletion of exon 10 of Nme7." (PMID 33916973, 2021).
hepatocellular carcinoma (4 papers, 2022 to 2025). A malignant tumor that arises from hepatocytes. "Recently, it was shown that NME7 might activate WNT/β-catenin signaling to regulate one-carbon metabolism in hepatocellular carcinoma." (PMID 39824631, 2025). "Although NME7 may be involved in hepatocellular carcinoma, whether the oncogenic roles of NME7 could be related to cilium and Hedgehog signaling remains to be defined in the future." (PMID 39824631, 2025). "In hepatocellular carcinoma (HCC), the positive regulator of the Wnt/β‐catenin signalling pathway is the nucleoside diphosphate kinase 7 (NME7), which promotes HCC progression." (PMID 37859585, 2023). "Conversely, MTHFD2 can also be activated by β-catenin in hepatocellular carcinoma, where MTHFD2 was found to mediate the oncogenic function of nucleoside diphosphate kinase 7 (NME7), which induces the Wnt/β-catenin pathway that activates MTHFD2 expression." (PMID 40604332, 2024).
primary ciliary dyskinesia (4 papers, 2018 to 2022). A rare, genetically heterogeneous, primarily respiratory disorder characterized by chronic upper and lower respiratory tract disease. "In summary, the CRISPR/Cas-9-mediated knock-out of the rat Nme7 gene resulted in a range of conditions consistent with the presentation of primary ciliary dyskinesia, supporting the previously implicated role of the centrosomally located Nme7 in ciliogenesis and the control of ciliary transport." (PMID 33916973, 2021). "In summary, the knock-out of the rat Nme7 gene resulted in a range of conditions consistent with the presentation of primary ciliary dyskinesia, supporting the previously implicated role of the centrosomally located Nme7 gene in ciliogenesis and control of ciliary transport." (PMID 33916973, 2021). "A knockout mouse for Nme7 shows situs inversus, and the loss of NME5, -7, or -8 causes primary ciliary dyskinesia." (PMID 30111592, 2018). "Functionally, Nme7 is found in ciliated structures and is a regulatory component of γ-tubulin ring complex, and this is reflected by the phenotypes observed in Nme7-/- mice and rats, consistent with primary ciliary dyskinesia." (PMID 34356103, 2021).
breast carcinoma (3 papers, 2017 to 2024). "Interestingly, NME7 has been recognized for its tumor-suppressive role in breast cancer, whereas GPX1 is linked to the regulation of tumor metastasis." (PMID 39664386, 2024).
Coronary arteriosclerosis (2 papers, 2021 to 2024). "Coronary arteriosclerosis shared 10 GWS genes with AD (BAG6, C6orf10, HLA-DQB1, HLA-DRA, HLA-DRB1, NDUFAF6, NME7, PLCG2, PRRC2A, and TRIB1), while myocardial infarction shared three genes with AD (HLA-DRA, PHB, and RP11-81K2.1)." (PMID 39201500, 2024).
Diabetes (2 papers, 2021 to 2022). "ANKRD12, NME7 and REV1 showed a 1.6 to 2.5-fold decreased expression in kidney glomeruli from individuals with DKD compared to healthy living donors (p < 0.01) in the Woroniecka Diabetes Dataset21." (PMID 36550108, 2022).
Airway obstruction (1 paper, 2021). Obstruction of conducting airways of the lung. "A carrier of the mutant Nme7 gene showed sinopulmonary symptoms, and a suggestive association was found between a loss of CNV involving Nme7 and equine recurrent airway obstruction." (PMID 33916973, 2021).
allergic rhinitis (1 paper, 2014). Inflammation of the nasal mucous membranes caused by an IgE-mediated response to external allergens. "Interestingly, there was also induction of ciliary genes (BBS1, NEBL, NME7) of which NEBL and NME7 in allergic rhinitis patients with or without asthma while BBS1 exclusively in patients with allergic rhinitis." (PMID 24475887, 2014).
breast invasive carcinoma (1 paper, 2020). "In this particular example, three separate eQTLs within a 50bp region (rs34176173, rs12085114, rs34016668) are found ~4.8k base pairs from the 3′ UTR of the gene NME7 in breast invasive carcinoma patient 3 (TCGA-BH-A0DT)." (PMID 32064050, 2020).
female infertility (1 paper, 2021). Diminished or absent ability of a female to achieve conception. "Further studies need to be conducted to elucidate the exact role of Nme7 in male and female infertility." (PMID 33916973, 2021).
Glucose intolerance (1 paper, 2021). Glucose intolerance (GI) can be defined as dysglycemia that comprises both prediabetes and diabetes. "Therefore, one might speculate that the renal tubular epithelium defects found in Nme7+/− rats could be related to impaired tubule renewal due to downstream effects of reduced Nme7 expression, even though the effects of the unfavorable obesity and glucose intolerance cannot be ruled out as well." (PMID 34356103, 2021).
rhinitis (1 paper, 2019). An inflammation of the mucous membrane lining the nose, usually associated with nasal discharge. "Normal male fertility and the absence of rhinitis/sinusitis observed in Nme7−/− mice indicates the importance of Nme7 in biogenesis of ependymal or embryonic node cilia, rather than the role in respiratory epithelium and spermatozoa cilia/flagella." (PMID 31877804, 2019).
tumor (2 papers, 2023 to 2024). "Notably, the upregulation of NME7 is known to improve survival outcomes and function in tumor suppression." (PMID 39664386, 2024).
metabolic disease (1 paper, 2021). A congenital disorder (due to inherited enzyme abnormality) or acquired (due to failure of a metabolically important organ) disorder resulting from an abnormal metabolic process. "Nme7 interacts directly with several entities related to lipid handling and insulin sensitivity, including the established nodes of metabolic diseases: the mitogen-activated protein kinase kinase kinase kinase 4 (Mapk4k4) and hepatocyte nuclear factor 4 (Hnf4)." (PMID 34356103, 2021).
NME7 also shares sentences with these, for which no sentence is quoted: situs inversus (4 papers); ciliopathies (2); asthma (1); breast tumor (1); cardiac diseases (1); dyslipidemia (1); heart failure (1); Infertility (1); myocardial infarction (1); Obesity (1); sinusitis (1); venous thromboembolism (1).